ITGAM (integrin subunit alpha M)
Diseases named in the same sentence as ITGAM in open-access papers (continued):
Sharing a sentence is not in itself a finding about the gene and the disease.
glioblastoma (31 papers, 2009 to 2026). The most malignant astrocytic tumor (WHO grade IV). "In addition, according to the database of the Ivy Glioblastoma Atlas Project, the distribution of PD-L1 was consistent with the distribution of the myeloid gene markers such as ITGAM, CD14, and CD68." (PMID 30333036, 2018).
ovarian carcinoma (30 papers, 2015 to 2026). A malignant neoplasm originating from the surface ovarian epithelium. "ChIP assays showed increased SMYD3 and H3K4me3 promoter binding at the ITGB6 and ITGAM gene loci in ovarian cancer spheroids and decreased binding with SMYD3 knockdown." (PMID 33637115, 2021). "CD83 highly-associated genes, such as ITGAM, IL1B, CYBB, PIK3R5, BTK, and OSM, ectopically express in ovarian cancer cells or tissues, involving in ovarian cancer progression, hypoxia networks, and the development of chemoresistance." (PMID 32823589, 2020). "In ovarian cancer, shRNA-mediated knockdown of SMYD3 decreases spheroid invasion and adhesion by suppressing integrin subunit beta 6 (ITGB6) and integrin subunit alpha M (ITGAM)." (PMID 39482529, 2024). "SMYD3 also facilitated implant metastasis of ovarian cancer cells via increasing the expression of ITGB6 and ITGAM." (PMID 37386026, 2023). "Siglec-9, the receptor of MUC16, had strong correlations with markers of neutrophil ITGAM, ITGB2, FCGR1A, FCGR2A, FCGR3A, analyzed with TCGA-OV database and ovarian cancer tissue RNA sequencing data." (PMID 37644468, 2023). "Protein-protein network interactions exhibited PTPRC, ITGAM, and CCR5 were most related to the modulation and function of the differentially expressed CBXs family members in ovarian cancer." (PMID 35155439, 2022). "In ovarian cancer spheroids, SMYD3 was found bind to H3K4me3 at the ITGB6 and ITGAM promoter regions to upregulate the expression of ITGB6 and ITGAM, which was verified to enhance the invasion and adhesion of ovarian cancer spheroids." (PMID 34621667, 2021). "Inhibition of ITGB6 and ITGAM directly also resulted in decreased ovarian cancer spheroid adhesion and invasion, and this was restored with re-expression of SMYD3, ITGB6, and ITGAM." (PMID 33637115, 2021). "ITGAM and ITGB6 have been confirmed to play critical roles in ovarian cancer invasion and implant metastasis." (PMID 33104706, 2020). "CD11b (ITGAM) and CD66b (CEACAM8), as surface molecular markers of neutrophil degranulation, were highly expressed after ovarian cancer organoids stimulation, which indicated that ovarian cancer cells could activate neutrophils." (PMID 37644468, 2023). "Using a 3D culture model to mimic the suspended growth conditions in ascites, we found that SMYD3 could enhance the adhesion and invasion of ovarian cancer spheroids and promote metastasis of ovarian cancer in vivo by upregulating the expression of ITGB6 and ITGAM." (PMID 34621667, 2021).
ischemic stroke (27 papers, 2013 to 2024). A stroke disorder caused by obstruction of blood flow to the brain, due to thrombotic (local blood clot formation) or embolic (due to a blood clot or other material traveling from another site) event. "The expression levels of both MMP9 and ITGAM were quantitatively assessed in the ischemic stroke (IS) and control groups." (PMID 38637126, 2024). "The findings of flow cytometry supported the evidence that ITGAM plays a multifaceted role in ischemic stroke pathophysiology." (PMID 38637126, 2024).
Autoimmunity (24 papers, 2014 to 2025). The occurrence of an immune reaction against the organism's own cells or tissues. "Given the observations of increased susceptibility to SLE in individuals bearing ITGAM SNPs, we first determined whether deficiency of CD11b in mice was sufficient to drive changes in the immune system consistent with development of autoimmunity." (PMID 35634296, 2022).
myocardial infarction (21 papers, 2013 to 2025). Gross necrosis of the myocardium, as a result of interruption of the blood supply to the area, as in coronary thrombosis. "The utility of ITGAM suggests that decreasing ITGAM expression may ameliorate myocardial infarction and that ITGAM gene polymorphism is a beneficial marker for determining cardiac cachexia in people with chronic congestive heart failure." (PMID 38970022, 2024).
gastric cancer (20 papers, 2013 to 2025). A primary or metastatic malignant neoplasm involving the stomach. "The mean methylation levels of gastric cancer tissues were higher than those of normal gastric tissues for two sites (TRIM15 and ITGAM) and lower for two sites (MSX2 and FAM38A), which were consistent with the results of the microarray analysis." (PMID 24944662, 2014). "qPCR results showed that the expression levels of ITGAM, MSX2 and FAM38A were upregulated in gastric cancer tissues, while the expression level of TRIM15 was downregulated (P<0.05)." (PMID 24944662, 2014). "Analysis of the results identified TRIM15, ITGAM, MSX2 and FAM38A as possible candidate sites clinically useful for the diagnosis and treatment of gastric cancer." (PMID 24944662, 2014). "TRIM15, ITGAM, MSX2 and FAM38A may be candidate genes for diagnosing gastric cancer." (PMID 24944662, 2014).
psoriasis (20 papers, 2016 to 2025). An autoimmune condition characterized by red, well-delineated plaques with silvery scales that are usually on the extensor surfaces and scalp. "In conclusion, this study associated SNP rs4597342 within 3'UTR of ITGAM with psoriasis susceptibility." (PMID 31211819, 2019). "SNP rs4597342 in 3'UTR of ITGAM influencing miR-21 binding may be considered a risk factor for psoriasis development." (PMID 31211819, 2019). "However, the major allele T of rs4597342 –ITGAM was associated with approximately 28% higher risk for psoriasis in comparison to the patients with the C allele (OR = 1.28, 95% CI 1.01–1.61, p = 0.037)." (PMID 31211819, 2019). "They found that SNP rs 4597342 in the 3’ non-coding region of the Integrin Subunit Alpha M (ITGAM) gene affected miR-21 binding, potentially serving as a risk factor for the development of psoriasis." (PMID 40861221, 2025). "The variability of ITGAM has been previously associated with SLE which has a nine times higher prevalence in women; it is thus possible that the effect of rs4597342 in psoriasis may be sex-dependent." (PMID 31211819, 2019). "We found one crossover locus of IL13 for psoriasis, two crossover loci BLK and ITGAM/ITGAX genes for SLE and four crossover loci near TFPI, CYP2A1, PECAM1, and CXCL12 for CAD data set." (PMID 32779262, 2020).
pulmonary fibrosis (19 papers, 2016 to 2025). Chronic progressive interstitial lung disorder characterized by the replacement of the lung tissue by connective tissue, leading to progressive dyspnea, respiratory failure, or right heart failure. "ITGAM promotes macrophage differentiation into the M2 subtype, a key cell population in the development of lung fibrosis." (PMID 40165483, 2025).
Alzheimer disease (18 papers, 2012 to 2023). A progressive, neurodegenerative disease characterized by loss of function and death of nerve cells in several areas of the brain leading to loss of cognitive function such as memory and language. "Genome-wide association studies of late-onset Alzheimer’s disease risk predicted OAS1, LAPTM5, ITGAM/CD11b and LILRB4 as four new risk genes for this neurodegenerative disease." (PMID 34943215, 2021). "ITGAM/CD11b was highlighted in recent genetic and functional analyses as likely being important for the progression of Alzheimer’s disease, whose expression was driven by SPI1/PU.1, and related to amyloid deposition in mice and humans." (PMID 32274467, 2019). "Most recently, inhibiting the interaction between the blood protein fibrinogen and ITGAM/CD11b reduced synaptic elimination and cognitive decline in a mouse model of Alzheimer’s disease, providing strong evidence that ITGAM/CD11b function contributes to disease development." (PMID 32274467, 2019). "These four genes, OAS1, LAPTM5, ITGAM/CD11b and LILRB4, have not been previously reported as having variants significantly associated with Alzheimer’s disease using traditional GWAS approaches." (PMID 32274467, 2019). "Most overrepresented molecular function annotations were amyloid beta binding activity—an activity presented by proteins such as ITGAM (also named CD11b) and TLR4 —as well as cytokine receptor binding activity, further linking the amyloid peptide to the innate immune response in Alzheimer's disease." (PMID 34335238, 2021). "Given the previous studies for ITGAM/CD11b, LAPTM5 and LILRB4, it is tempting to speculate that they are involved in phagocytic processes involving synapses which are known to be reactivated during Alzheimer’s disease progression." (PMID 32274467, 2019).
lupus nephritis (17 papers, 2013 to 2025). Glomerulonephritis in the context of systemic lupus erythematosus. "Since the susceptibility allele (A) at rs1143679 in ITGAM is also associated with lupus nephritis development, our observations of increased anti-dsDNA IgG/IgM ratio in this group provide a causative relationship between genotype and phenotype." (PMID 26950932, 2016). "In the context of lupus nephritis, ITGAM is thought to regulate negatively the activities of innate immune cells such as macrophages and neutrophils within pro-inflammatory signaling pathways." (PMID 38413872, 2024). "An additional six genes showed an association with lupus nephritis with p <0.001 (PMS2, TNIP1, CARD11, ITGAM, BLK and IRAK1)." (PMID 24386384, 2013). "Therefore, ITGAM-targeting agonists represent a potential treatment for lupus nephritis." (PMID 38413872, 2024). "Genome-wide association studies have identified loss-of-function polymorphisms in the CD11b-encoding gene ITGAM that are strongly associated with SLE and lupus nephritis; however, it is not known whether these polymorphisms act alone to induce disease or in concert with other risk alleles." (PMID 35634296, 2022).
myeloma (17 papers, 2012 to 2024). "ITGAM, ITGB2 genes play a pivotal role in cell adhesion in multiple myeloma and are reported as potential diagnostic markers." (PMID 33946372, 2021). "From a bioinformatics analysis, ITGAM and ITGB2 were also up-regulated in myeloma and involved in cytokine-cytokine receptor interaction, innate immune response and inflammatory response that were similar to our results." (PMID 35501867, 2022).
Cognitive impairment (16 papers, 2015 to 2025). Abnormal cognition is characterized by deficits in thinking, reasoning, or remembering. "Across all cognitively unimpaired (CU) individuals and patients with mild cognitive impairment (MCI), SMOC1 and ITGAM showed the strongest positive associations with global Aβ-PET levels, all associations being independent of tau-PET levels." (PMID 39187705, 2024).
periodontitis (14 papers, 2018 to 2025). An acute or chronic inflammatory process that affects the tissues that surround and support the teeth. "ITGAM was found to be up-regulated in gingival tissues of periodontal diseased patients." (PMID 35450027, 2022).
renal fibrosis (13 papers, 2012 to 2024). A final common manifestation of a wide variety of chronic kidney diseases characterized by glomerulosclerosis and tubulointerstitial fibrosis. "Previous studies reported that ITGAM overexpression was associated with macrophage infiltration and renal fibrosis." (PMID 38911067, 2024). "In this study, we report that macrophage ITGAM contributes to renal fibrosis in hyperuricemia‐related CKD." (PMID 38911067, 2024). "Taking our results together, the functional role of ITGAM in contributing to renal fibrosis through promoting M2 polarization could be inferred." (PMID 38911067, 2024). "However, it is not well elucidated whether ITGAM regulated macrophage M2 polarization in renal fibrosis and signaling pathways involved." (PMID 38911067, 2024).
rheumatoid arthritis (13 papers, 2016 to 2025). A chronic, systemic autoimmune disorder characterized by inflammation in the synovial membranes and articular surfaces. "Regarding rheumatoid arthritis (RA), the ITGAM R77H SNP has seldom been evaluated and the finding of association identified to SLE has not been replicated in this autoimmune disease (AD)." (PMID 31774828, 2019).
osteosarcoma (9 papers, 2012 to 2025). A usually aggressive malignant bone-forming mesenchymal neoplasm, predominantly affecting adolescents and young adults. "The upregulation of immune-related genes such as CD86, FCER1G, and ITGAM suggests involvement of immune activation and inflammatory signaling within the osteosarcoma microenvironment." (PMID 40895569, 2025). "Consistent with our observations from TCGA and GTEx, most hub genes—including PLEK, CYBB, CXCR4, and ITGAM—were significantly upregulated in osteosarcoma samples compared to normal controls." (PMID 40895569, 2025). "Similarly, CDH4 deficiency impacts the invasion of human osteosarcoma cells, and epithelial ovarian cancer (EOC) invasion is mediated by ITGAM." (PMID 34105233, 2021).
renal cell carcinoma (9 papers, 2013 to 2024). "IL2 controlling ITGAM, which in complex with CD14 (both are cell surface markers,), are specific in C10 and this type I cytokine can be associated with durable regression in metastatic melanoma and renal cell carcinoma." (PMID 34238310, 2021).
type 2 diabetes (9 papers, 2018 to 2025). "DAVID was used to identify the functions of these genes, and TIRAP, TNFRSF1A, CASP1, CSF1, and ITGAM were associated with type 2 diabetes." (PMID 39194753, 2024). "We further measured and compared the gene expression of CXCR1, SELL, ITGA4, ITGAM, NCF4, ARHGAP3, and CLDN15 in neutrophils from 5 type 2 diabetes patients within 1 year from diagnosis and 5 age- and sex-matched healthy control subjects." (PMID 33391182, 2020).
co-infection (8 papers, 2014 to 2025). "Notably, TGF-β signaling (TGFB1-TGFBR1-TGFBR2) was extinguished during HIV-mono infection yet reappeared in co-infection, whereas IL16-CD4 and CD40LG-(ITGAM/ITGB2) interactions disappeared with HIV-mono and did not recover, underscoring stage-specific rewiring of T-cell communication networks." (PMID 41394852, 2025).
helminth infection (7 papers, 2010 to 2025). "ITGAL and ITGAM are bound by neutrophil inhibitory factor (NIF), an antiadhesive glycoprotein isolated from the canine hookworm Ancylostoma caninum, suggesting that leukocyte integrins are relevant to the immune response to helminth infections." (PMID 20807397, 2010).
mesothelioma (7 papers, 2016 to 2025). A usually malignant and aggressive neoplasm of the mesothelium which is often associated with exposure to asbestos. "Noteworthy observations included a significant infiltration of M1 macrophages and CD4 + T cells in mesothelioma, with genes SOAT1, MNDA, and ITGAM showing a positive correlation with the level of M1 macrophage infiltration." (PMID 40223054, 2025).
prion disease (7 papers, 2019 to 2026). A transmissible disease that is caused by a protein that is able to induce abnormal folding of normal cellular proteins, leading to characteristic spongiform brain changes, which are associated with neuronal loss without an inflammatory response. "This suppression, along with reduced expression of integrins such as ITGAM and ITGB2 (integrin), likely contributed to the enrichment of infection-related pathways, including those associated with prion disease and Staphylococcus aureus infection." (PMID 41155303, 2025).
steatosis (7 papers, 2013 to 2025). Increased lipid within the cytoplasm of cells. "To confirm these conclusions in vitro, we cultured HDF cells and induced steatosis using sodium palmitate (10 mmol/L) and sodium oleate (10 mmol/L) for 24 h, and detected expression levels of ITGAM, ITGAL, and NLRC4 in cells." (PMID 36457728, 2022).
nephritis (6 papers, 2014 to 2023). Inflammation of renal tissue. "Moreover, complement receptor genes CR1, ITGAM, ITGAX and ITGB2 showed a significant link between expression and kidney inflammation." (PMID 34326417, 2021).
neuroblastoma (6 papers, 2021 to 2024). Neuroblastoma (NB) is the most common solid, extracranial childhood tumor. "We analyzed the expression of endothelial markers (EGFL7, FLT1, PTPRB33), mesenchymal cells (COL1A2, COL1A1, PDGFRB34,35) and immune markers (ITGAM, CD247, PTPRC36–38) in MYCN-amplified neuroblastoma patient samples (with at least 90% tumor purity) and tumors from Protocol #4." (PMID 39367051, 2024).
Cachexia (5 papers, 2018 to 2024). Severe weight loss, wasting of muscle, loss of appetite, and general debility related to a chronic disease. "The main factor contributing to the development of cachexia is the ongoing inflammatory process mediated by genes (e.g. Integrin Subunit Alpha M—ITGAM)." (PMID 34635743, 2021).
cardiac hypertrophy (5 papers, 2019 to 2025). "It has been documented that ITGAM is potentially related to cardiac hypertrophy." (PMID 38970022, 2024).
Cirrhosis (5 papers, 2020 to 2023). A chronic disorder of the liver in which liver tissue becomes scarred and is partially replaced by regenerative nodules and fibrotic tissue resulting in loss of liver function. "It is plausible that the positive association between ITGAM levels and cirrhosis relates to the role of integrins in the contraction of myofibroblasts." (PMID 36358697, 2022). "We identified two individual proteins (DEFA-1, and ITGAM) that were positively associated, and two individual proteins (CCL11 and SCF) that were negatively associated with the development of cirrhosis." (PMID 36358697, 2022). "Regarding HCC risk, development of HCC showed inverse associations compared to persons with cirrhosis with two proteins, including DEFA-1 [ORC2v.C1 = 0.06 (95% CI: 0.02–0.20)] and ITGAM [ORC2v.C1 = 0.20 (95% CI: 0.08–0.40)]." (PMID 36358697, 2022). "In contrast to cirrhosis, DEFA-1 and ITGAM levels were inversely associated with HCC risk." (PMID 36358697, 2022). "However, the magnitude of association with late cirrhosis development was attenuated for DEFA-1 and ITGAM." (PMID 36358697, 2022).
IgA nephropathy (5 papers, 2021 to 2024). "Although there are isolated reports of complement pathway risk alleles in IgA glomerulonephritis, the only major ones are ITGAM and ITGAX that code for integrins that facilitate complement-dependent phagocyte activation and immune complex clearance." (PMID 36316518, 2022). "Other loci associated with IgA nephropathy, such as such as DEFA, TNFSF 13, VAV 3, ITGAM-ITGAX, and PSMB 8, encode proteins involved in maintaining the intestinal mucosal barrier or regulating mucosal immune responses." (PMID 39421866, 2024). "ITGAM–ITGAX (rs11150612, rs11574637), VAV3 rs17019602, CARD9 rs4077515, DEFA (rs2738048, rs10086568), and HORMAD2 rs2412971 are mucosal immune defence polymorphisms, that have an impact on IgA production, described as risk loci for IgA nephropathy (IgAN)." (PMID 37685869, 2023).
liver cancer (5 papers, 2021 to 2025). An epithelial or non-epithelial malignant neoplasm that arises from the liver. "The expression of FCN2 was negatively correlated with the M1 macrophage biomarker (IRF5), neutrophil biomarker (ITGAM), and DC biomarker (ITGAX) in liver cancer." (PMID 36425563, 2022).